CTSG (cathepsin G)
Description:
Serine protease with trypsin- and chymotrypsin-like specificity. Also displays antibacterial activity against Gram-negative and Gram-positive bacteria independent of its protease activity. Prefers Phe and Tyr residues in the P1 position of substrates but also cleaves efficiently after Trp and Leu. Shows a preference for negatively charged amino acids in the P2' position and for aliphatic amino acids both upstream and downstream of the cleavage site. Required for recruitment and activation of platelets which is mediated by the F2RL3/PAR4 platelet receptor. Binds reversibly to and stimulates B cells and CD4(+) and CD8(+) T cells. Also binds reversibly to natural killer (NK) cells and enhances NK cell cytotoxicity through its protease activity. Cleaves complement C3. Cleaves vimentin (By similarity). Cleaves thrombin receptor F2R/PAR1 and acts as either an agonist or an inhibitor, depending on the F2R cleavage site. Cleavage of F2R at '41-Arg-|- Ser-42' results in receptor activation while cleavage at '55-Phe-|-Trp-56' results in inhibition of receptor activation. Cleaves the synovial mucin-type protein PRG4/lubricin. Cleaves and activates IL36G which promotes expression of chemokines CXCL1 and CXLC8 in keratinocytes. Cleaves IL33 into mature forms which have greater activity than the unprocessed form. Cleaves coagulation factor F8 to produce a partially activated form. Also cleaves and activates coagulation factor F10. Cleaves leukocyte cell surface protein SPN/CD43 to release its extracellular domain and trigger its intramembrane proteolysis by gamma-secretase, releasing the CD43 cytoplasmic tail chain (CD43-ct) which translocates to the nucleus. Cleaves CCL5/RANTES to produce RANTES(4-68) lacking the N-terminal three amino acids which exhibits reduced chemotactic and antiviral activities. During apoptosis, cleaves SMARCA2/BRM to produce a 160 kDa cleavage product which localizes to the cytosol. Cleaves myelin basic protein MBP in B cell lysosomes at '224-Phe-|-Lys-225' and '248-Phe-|-Ser-249', degrading the major immunogenic MBP epitope and preventing the activation of MBP-specific autoreactive T cells. Cleaves annexin ANXA1 and antimicrobial peptide CAMP to produce peptides which act on neutrophil N-formyl peptide receptors to enhance the release of CXCL2. Acts as a ligand for the N-formyl peptide receptor FPR1, enhancing phagocyte chemotaxis. Has antibacterial activity against the Gram-negative bacteria N.gonorrhoeae and P.aeruginosa. Likely to act against N.gonorrhoeae by interacting with N.gonorrhoeae penA/PBP2. Exhibits potent antimicrobial activity against the Gram-positive bacterium L.monocytogenes. Has antibacterial activity against the Gram-positive bacterium S.aureus and degrades S.aureus biofilms, allowing polymorphonuclear leukocytes to penetrate the biofilm and phagocytose bacteria. Has antibacterial activity against M.tuberculosis. Mediates CASP4 activation induced by the Td92 surface protein of the periodontal pathogen T.denticola, causing production and secretion of IL1A and leading to pyroptosis of gingival fibroblasts. Induces platelet aggregation which is strongly potentiated in the presence of ELANE. (Microbial infection) Inhibited reversibly by S.aureus serine protease inhibitors Eap, EapH1 and EapH2, impairing microbicidal activity in neutrophils.
Synonyms: CG; CATG
Tractability: Small molecule: a structure with a bound ligand is known; a high-quality ligand is known; it belongs to a druggable protein family. Antibody: UniProt places it where antibodies can reach, with high confidence; its Gene Ontology location is reachable by antibodies, with high confidence; UniProt predicts a signal peptide or a membrane-spanning region. PROTAC: its protein half-life has been measured; a small molecule that binds it is known.
Target class: Serine protease; Enzyme; Serine protease PA clan; Serine protease S1A subfamily; Protease
Gene: Protein-coding gene on chromosome 14 (24,573,518 to 24,576,250, reverse strand). Ensembl gene ENSG00000100448.
Subcellular location: Cell membrane; Cytoplasmic granule; Secreted; Cytoplasm, cytosol; Lysosome; Nucleus
Pathways (Reactome):
Immune System: Antimicrobial peptides; Interleukin-1 processing; Neutrophil degranulation
Disease: Purinergic signaling in leishmaniasis infection; Suppression of apoptosis
Extracellular matrix organization: Activation of Matrix Metalloproteinases; Degradation of the extracellular matrix
Metabolism of proteins: Metabolism of Angiotensinogen to Angiotensins; Regulation of Insulin-like Growth Factor (IGF) transport and uptake by Insulin-like Growth Factor Binding Proteins (IGFBPs)
Gene Ontology:
Molecular function: caspase binding; heparin binding; peptidase activity; protein binding; receptor ligand activity; serine-type endopeptidase activity; serine-type peptidase activity
Biological process: antibacterial humoral response; biofilm matrix disassembly; cellular response to lipopolysaccharide; defense response to Gram-negative bacterium; defense response to Gram-positive bacterium; monocyte chemotaxis; negative regulation of T cell activation; neutrophil activation; platelet activation; positive regulation of platelet aggregation; protein processing; proteolysis; angiotensin maturation; cytokine-mediated signaling pathway; extracellular matrix disassembly; immune response; protein maturation; purinergic nucleotide receptor signaling pathway
Cellular component: cytoplasmic stress granule; cytosol; extracellular exosome; extracellular matrix; extracellular region; lysosome; membrane; nucleus; plasma membrane; secretory granule; azurophil granule lumen
Genetic constraint (gnomAD): Loss-of-function variants: 23 observed, 23.42 expected, observed/expected ratio (o/e) 0.98, 90% interval 0.71 to 1.39. The upper end of that interval is the gene's LOEUF score, 1.39, which puts it in group 5 of 6, group 1 being the genes least tolerant of losing a copy. Missense variants: 312 observed, 338.78 expected, observed/expected ratio (o/e) 0.92, 90% interval 0.84 to 1.01. Synonymous variants: 140 observed, 134.63 expected, observed/expected ratio (o/e) 1.04, 90% interval 0.91 to 1.2.
Homologues: Orthologues: chimpanzee CTSG (97% identical), macaque CTSG (85% identical), mouse Ctsg (68% identical), rat Ctsg (67% identical), dog CTSG (63% identical), rabbit CTSG (53% identical), tropical clawed frog ctsg (39% identical). Paralogues in human: GZMB (55% identical), GZMH (55% identical), CMA1 (50% identical), KLK13 (36% identical), AZU1 (35% identical), KLK6 (32% identical).
Diseases named in the same sentence as CTSG in open-access papers:
CTSG is named in the same sentence as 181 diseases in open-access papers, as found by Europe PMC text mining. Sharing a sentence is not in itself a finding about the gene and the disease. The quoted sentences say what the papers report.
breast carcinoma (16 papers, 2009 to 2024). "Cathepsin G is a serine protease involved in degradation of extracellular components, antigen presentation, and leukemogenesis, and is associated with aggressive phenotypes in acute lymphoblastic leukemia and breast cancer." (PMID 34621666, 2021). "It has been demonstrated that CTSG has an inhibitory effect on colorectal cancer cells by controlling the activity of the anti-apoptotic signaling pathway, and CTSG is highly expressed in breast cancer cells." (PMID 39080685, 2024). "Positive staining was demonstrated on human tissues: placenta for cathepsin B, breast carcinoma for cathepsin D and tonsil for cathepsin G." (PMID 34409065, 2021). "Human tissues used for positive controls demonstrated the expected staining patterns for cathepsin B on placenta, cathepsin D on breast carcinoma, cathepsin G on tonsil." (PMID 34621666, 2021). "Cathepsin G (CTSG), an azurophil granule protease, can lead to breast cancer cell migration and can enter tumor endosomes by binding to a cell surface receptor." (PMID 33323544, 2020). "Positive controls for cathepsin B (brown), cathepsin D (brown) and cathepsin G (brown) demonstrated the expected staining patterns in human placenta, breast carcinoma and mouse bone marrow, respectively." (PMID 30177970, 2018). "Cathepsin G-mediated activation of MMP–9 at the tumor-bone interface promotes bone destruction in breast cancer." (PMID 26440411, 2015). "Here, we show that contact inhibition of cell movement and cell condensation is induced by cathepsin G in MCF-7 human breast cancer cells." (PMID 19920860, 2009). "Here, we demonstrate that cathepsin G induces cell-cell adhesion of MCF-7 human breast cancer cells resulting from the contact inhibition of cell movement on fibronectin but not on type IV collagen." (PMID 19920860, 2009). "In addition, CTSG has been informed as a cancer inhibitor gene in breast cancer 27 and bladder cancer." (PMID 37151875, 2023). "In addition to their role in tumor cell proliferation, NET-derived molecules such as Cathepsin G (CG) and NE were reported to promote invasion and migration of breast cancer cells." (PMID 31616408, 2019). "We previously observed that cathepsin G induces multicellular spheroids of mammary tumor cells." (PMID 19920860, 2009). "In human breast cancer MCF-7 cells, CTSG stimulates cell migration and multicellular aggregation using E-cadherin." (PMID 35935989, 2022). "We previously found that a neutrophil serine protease, cathepsin G, weakens adherence to culture substrates and induces E-cadherin-dependent aggregation of MCF-7 human breast cancer cells through its protease activity." (PMID 24803743, 2014). "CTSG is also capable of activating pro-MMP-9, that cleaves and releases active transforming growth factor-β (TGFβ), MMP-13 and RANKL at the tumor-bone interface of mammary tumor-induced osteolytic lesions." (PMID 31647805, 2019). "To know whether the transient pattern of E-cadherin/catenin complex formation induced by cathepsin G is restricted to MCF-7 cells, we examined complex formation in BALB-MC.E12 mouse mammary tumor cells." (PMID 19920860, 2009). "Cathepsin G, a serine protease secreted by activated neutrophils, promotes E-cadherin/catenin complex formation on fibronectin and thereby induces cell–cell adhesion of MCF-7 human breast cancer cells, suggesting that cathepsin G plays a role in tumor development and metastasis." (PMID 35784290, 2022). "In the present study, we demonstrate that cathepsin G induces contact inhibition of cell movement and cell condensation of MCF-7 human breast cancer cells on fibronectin but not on type IV collagen." (PMID 19920860, 2009).
COVID-19 (16 papers, 2020 to 2025). A disease caused by infection with severe acute respiratory syndrome coronavirus 2. "As a consequence of this inflammatory milieu underlying STEMI and COVID-19, neutrophils adhere to capillary endothelium together with decondensed chromatin and antimicrobial proteins such as elastase and cathepsin G, causing formation of plugs in microvessels." (PMID 33126723, 2020). "Mainly, in the different articles, the following types of proteases were analyzed, and it was observed that a high level of furin, cathepsin B, cathepsin L, and cathepsin G may increase the risk of COVID-19 complications." (PMID 35224542, 2022). "It has also been proposed that patients with periodontitis show increased levels of different proteases (furin, cathepsin B, cathepsin L, cathepsin G), which may favour a more severe COVID-19, since they have been shown to increase the risk of complications in COVID-19 patients." (PMID 37133697, 2023). "At the onset of the COVID-19 pandemic, elastase and cathepsin G were highly upregulated in nasopharyngeal swabs from SARS-CoV-2-infected patients, which was directly associated with neutrophil degranulation and NETosis." (PMID 35997950, 2022). "For instance, while reducing the correlation between DEGs including IL10, CXCL8, NFKB1, ARG1, and SOD2, new strong associations appeared between ELANE, DEFA4, AZU1, CTSG, and LCN2, with an overall tendency to higher relationships amid neutrophil-mediated immunity genes in COVID-19 patients." (PMID 35269470, 2022). "The COVID-19 neutrophils likewise exhibited >5-fold elevated neutrophil elastase activity on a per-cell basis, consistent with the elevated transcript levels of cathepsin G (CTSG) and DEFA1, and the de-compacted, DAPIbright chromatin." (PMID 35081105, 2022). "In addition, targeting other neutrophil proteins like Azurocidin (AZU1) and cathepsin G (CTSG) that are elevated in nasopharyngeal swaps of COVID-19 patients, as well as the inhibition of NET formation, have been suggested to alleviate SARS-CoV-2 symptoms." (PMID 35269470, 2022). "Meanwhile, LF rebalanced the platelet count, which may enhance the COVID-19 viral clearance, may increase the platelets production and activation via enhancing cathepsin G, and consequently promote the innate immune responses during acute inflammation through cathepsin G." (PMID 33954061, 2021). "Furthermore, the genes ELANE, AZU1, MPO, PRTN3, CTSG, and TCN1 were shown to be significantly altered in patients with COVID-19, and our automatically prepared knowledge base highlights all of them as associated with COVID-19 with “medium” or “low” confidence." (PMID 33055059, 2020). "Since ACT irreversibly forms complexes with cathepsin G, further research is needed to determine whether ACT activity protects against or contributes to severe COVID-19." (PMID 39949890, 2025). "The roles of proteinase 3 and cathepsin G in SARS-CoV-2 infection and related cell death are significantly less well studied, as most studies have focused on elastase; therefore, further efforts are needed to link the individual activities of these enzymes to COVID-19 pathology." (PMID 35997950, 2022).
leukemia (12 papers, 2011 to 2026). A malignant (clonal) hematologic disorder, involving hematopoietic stem cells and characterized by the presence of primitive or atypical myeloid or lymphoid cells in the bone marrow and the blood. "The earliest transgenic models expressed PML-RARA under control of sequences that regulate the expression of the human cathepsin G gene in myeloid cells, though leukemia penetrance was low at 30% and disease latency was prolonged." (PMID 35756660, 2022). "Kasumi‐1 harbors oncogenic fusion of RUNX1‐ETO, which is one of the most common genetic alterations in leukemia and suppresses the expression of Cathepsin G and elastase in the lysosomes." (PMID 34407310, 2022). "Immunohistochemistry was performed to assess expression of vascular endothelial growth factor (VEGF), cathepsin G, tissue-type plasminogen activator, urokinase-type plasminogen activator, urokinase-type plasminogen activator receptor, and tissue factor in leukemia cells." (PMID 42023399, 2026). "In Cathepsin-G-PML-RARα knock-in mice, c-Kit+Gr-1+ cells containing promyelocytes are thought to confer the property of self-renewal and capable of engendering leukemia in secondary recipient mice." (PMID 34117212, 2021). "Cathepsin G is a serine protease largely restricted to the myeloid lineage and is expressed in high levels within azurophil granules in AML blasts and leukemia stem cells and during the promyelocyte stage of neutrophil development." (PMID 29422892, 2017). "Cathepsin G (CG) is a myeloid azurophil granule protease that is highly expressed by acute myeloid leukemia (AML) blasts and leukemia stem cells." (PMID 29422892, 2017). "CTSG is broadly expressed in acute myeloid leukemia (AML) blasts and leukemia stem cells." (PMID 35111390, 2022). "Studies have shown that CTSG down-regulation was observed in AML patients, and its targeting and inhibition may offer a way for leukemia cells to elude cellular surveillance systems by inhibiting the breakdown of foreign proteins, and consistent with our research findings." (PMID 35568859, 2022).
Sepsis (12 papers, 2018 to 2025). Sepsis is defined as life-threatening organ dysfunction caused by a dysregulated host response to infection. "Prior time series analysis of septic patients identified three genes in the elastase family (ELANE, CTSG, PRTN3) and DEFA4 as candidate biomarkers for sepsis, while other studies likewise implicated NETosis genes including ALPL." (PMID 41385588, 2025). "It has been found that cathepsin G and chymotrypsin exist in tissues, which can convert Ang I into Ang II, was found highly expressed in sepsis, promoting the local production of Ang II, increasing the expression of Ang II in lung and kidney." (PMID 39178201, 2024). "In the context of inflammation in sepsis, bikunin may inhibit a number of tissue damaging serine proteases which are released from neutrophils such as elastase or cathepsin G." (PMID 38698864, 2024). "We found the upregulated CTSG expression in sepsis, which might be a regulator of inflammation response during sepsis." (PMID 36860871, 2023). "Administration of ELANE and CTSG induces lung inflammation, whereas knockout of both ELANE and CTSG decreases mortality rate and lung injury in a murine sepsis model." (PMID 30174607, 2018). "A recent study further showed that luteolin (20 mg/kg) inhibits the AKT1/nitric oxide synthase 2/cathepsin G (AKT1/NOS2/CTSG) axis, thereby blocking caspase-11 and GSDMD activation, leading to reduced IL-1β and TNF-α release, thus mitigating sepsis-induced pulmonary injury." (PMID 41394141, 2025). "Next, the ROC curves show that the ITGAM, CXCR2, and FCGR3B expression levels provide high accuracy for classifying the Sepsis and Control group (AUC > 0.9); MMP9, MPO, and CTSG expression levels exhibit moderate accuracy for this classification (0.7 < AUC < 0.9)." (PMID 41259376, 2025). "Second, there are many ligands of FPR1, including the HSP, lipoxin A4, cathepsin G and so on, we only detected the concentration of MT-ND6 and ANXA1 in this study, which was insufficient to revel the comprehensive functions of FPR1 in sepsis." (PMID 39611143, 2024). "Furthermore, animal models of lung injury have shown that FOXM1 is essential in regulating neutrophil response and secretion of MPO and cathepsin G, both of which were enriched in neonates that did not survive sepsis." (PMID 40655143, 2025). "However, there were no changes in the expression levels of CTSC, CTSG, PRTN3 and ELANE in neutrophils during sepsis compared to those from healthy controls." (PMID 33868254, 2021).
acute myeloid leukemia (8 papers, 2017 to 2025). Acute myeloid leukemia (AML) is a group of neoplasms arising from precursor cells committed to the myeloid cell-line differentiation. "CTSG encodes a member of the peptidase S1 protein family, which is found broadly expressed in acute myeloid leukemia and may participate in the connective tissue remodeling at the site of inflammation." (PMID 33123575, 2020). "In addition, CTSG is associated with tumor angiogenesis and metastasis, participating in host defense and neutrophil-related immune responses, and serving as a target of immunotherapy for acute myeloid leukemia (AML)." (PMID 35935989, 2022). "Besides, high CTSG expression was correlated with poor outcomes in treating acute myeloid leukemia (AML)." (PMID 33323544, 2020). "CTSG (Cathepsin G) is thought to be an effective therapeutic target in acute myeloid leukemia patients and could rapidly enhance NK cytotoxicity." (PMID 32513106, 2020). "Many studies have indicated that CTSG, a member of the Cathepsin family, functions as a cancer suppressor in many tumors, inhibiting the malignant features and cancers development, like breast, bladder, oral squamous cell cancer, and acute myeloid leukemia 26-29." (PMID 37151875, 2023). "Our group has identified azurophil granule serine proteases, specifically cathepsin G (CG), neutrophil elastase (NE), and proteinase 3 (P3), as immunotherapeutic targets in acute myeloid leukemia (AML) and has developed immunotherapies that target these proteases." (PMID 29422892, 2017).